RUNX1 (RUNX family transcription factor 1)
Diseases named in the same sentence as RUNX1 in open-access papers (continued):
Sharing a sentence is not in itself a finding about the gene and the disease.
leukemia (continued). "Known as one of the most frequently mutated genes in human leukemia, RUNX1 is originally identified to have a role in hematopoiesis." (PMID 34294773, 2021). "Mutations of RUNX1 often become a first-hit mutation in pre-leukemia conditions or myeloid dysplastic syndrome." (PMID 34421907, 2021). "At present, more than 50 chromosome translocations that affect RUNX1 function have been identified, most of which cause maturation arrest of myeloid cells and even leukemia." (PMID 33434583, 2021). "All RUNX1 SNV and indels resulted somatically acquired, excluding a familial predisposition leukemia with one inherited RUNX1 mutation, which is an increasingly recognized and often underdiagnosed condition." (PMID 34540694, 2021). "We found that STAG2 mutation in K562 leukemia cells increased chromatin accessibility at BRD4 binding sites at the RUNX1 and ERG genes." (PMID 34202641, 2021). "Further, the RUNX1-D171N mutation collaborates with overexpression of Evi1 to induce leukemia in mice." (PMID 34944812, 2021). "While confirming previous findings about the role of certain co-occurring mutations (RAS and RUNX1) in primary resistance to IDHi9, we additionally revealed that leukemia stemness is associated with IDHi primary resistance." (PMID 33972549, 2021). "RUNX1 mutations caused by chromosomal rearrangements, fusion proteins, or point mutations are commonly observed in leukemia." (PMID 34434964, 2021). "Since THP-1 cells are monocytic leukemia, to clarify if our finding is caused by different cell types or direct evidence of Runx1 function in leukemia, we further compared THP-1 cells against monocyte." (PMID 34434964, 2021). "In a myeloid-BP patient, the RUNX1 mutation was the sole leukemia-associated mutation identified both in CP (SNV) and progression (SNV and LOH) samples." (PMID 32782381, 2021). "RUNX1 is a key player in definitive hematopoietic stem cell formation and is frequently mutated in leukemia." (PMID 34831147, 2021). "Results from this study showed that RUNX1 loss resulted in predisposition to leukemia whereas haploinsufficiency led to defects in primitive erythropoiesis and megakaryopoiesis, and caused thrombocytopenia with no leukemia." (PMID 34685678, 2021). "The region of chromosome 21 increasing the risk of leukemia contains genes involved in hematopoiesis, such as RUNX1, ETS2, ERG, and DYRK1A." (PMID 34359655, 2021). "For example, the transcription factor RUNX1, which is frequently mutated in different types of human leukemia, is directly involved in the expression of ribosomal proteins (RPs), genes, and rRNA in HSCs." (PMID 33946178, 2021). "Our results pave the way for further exploration of the molecular mechanisms associated with dysregulated RUNX1 in leukemia." (PMID 34434964, 2021). "A previous study showed that RUNX1 mutation promotes leukemogenesis of myeloid malignancies in ASXL1+ leukemia and is associated with adverse prognoses of patients with de novo AML." (PMID 34627254, 2021). "For example, the function of the transcription factor RUNX1/AML1, frequently mutated in myelodysplastic syndrome and human leukemia, is directly linked to the expression of ribosomal proteins and rRNAs." (PMID 34842767, 2021). "RUNX1 was involved in the development of normal hematopoiesis, while its mutation and translocations had been associated with several types of leukemia." (PMID 33937021, 2021). "Loss of wild-type RUNX1 significantly reduces cell proliferation in CBFB-MYH11 fusion-induced leukemia cells, E2A-PBX1-induced ALL, and MLL-fusion-induced AML." (PMID 34434964, 2021). "Exon 8 frameshift mutations were highly associated with CBFB/MYH11-rearranged leukemia, while point mutations affecting position D816 were correlated with RUNX1/RUNX1T1 leukemia." (PMID 31896782, 2020).
leukemia (continued). "Elucidation of the deregulated intracellular signaling pathways downstream of CSF3R and RUNX1 mutations will help to identify druggable targets, with the goal of eliminating leukemia-predisposed HSPCs and/or specifically targeting CN/AML blasts." (PMID 32821971, 2020). "Taken together, these studies showed that RUNX1‐ETO alone is unable to cause leukaemia and additional mutations are required for leukaemogenesis." (PMID 34766123, 2020). "A loss of function of RUNX1 has been shown to impair the differentiation of both lymphoid and myeloid lineages, often resulting in the development of leukaemia." (PMID 32992503, 2020). "Functional disruption of RUNX1 usually occurs by chromosomal translocation, point mutation, or deletion in leukemia and some solid tumors." (PMID 32498288, 2020). "The identification of cooperative CSF3R and RUNX1 mutations in a majority of CN patients with overt MDS or AML brought us one step closer to understanding leukemia development." (PMID 32821971, 2020). "In a quantitative manner, these data are in line with previous EMSA results, supporting the correlation between reduced DNA-binding affinity, decreased RUNX1 activity in gene regulation, and increased predisposition to leukemia in the clinic." (PMID 31048839, 2019). "The present study demonstrated the biological and functional evidence for the critical role of RUNX1-MT in ASXL1-mutated leukemia in the pathogenesis of myeloid malignancies." (PMID 31640815, 2019). "Taken together, we found that the gain-of-function of RUNX1-MT enhanced among ASXL1-mutated leukemia in vitro and in vivo." (PMID 31640815, 2019). "GM-CSF signaling deficiency is favorable for leukemia development driven by Runx1-Runx1t1 in mouse models." (PMID 31817911, 2019). "A striking feature of RUNX1 alterations is the mutual exclusivity of RUNX1 sequence mutation and chromosomal aberrations in leukemia which we will discuss later." (PMID 30654457, 2019). "The current paradigm for RUNX1 mutation-mediated leukemia initiation is due to insufficient activity of wild-type (WT) RUNX1 for hematopoiesis, which causes accumulation of immature blood cells as well as insufficient numbers of functional blood cells." (PMID 31048839, 2019). "RUNX1 is a gene that, in pathological conditions, participates in several chromosomal translocations associated with leukemia." (PMID 31366376, 2019). "Our findings demonstrate multiple mechanisms by which transformed cells escape from RUNX growth suppression and provide a rationale for the contrasting secondary collaborating mutations required for TEL‐RUNX1 and RUNX1‐ETO associated leukemias." (PMID 29052866, 2018). "The patient (UPN 37) who had least increase in variant allele frequency of DNMT3A mutation during disease progression acquired RUNX1 mutation at leukemia transformation." (PMID 29619119, 2018). "These lncRNAs are well studied in cancer: FENDRR for its prognostic value and its involvement in gastric cancer metastasis and CASC15 for its regulation of SOX4 in RUNX1-rearranged leukemia and harboring a risk SNP for susceptibility of neuroblastoma." (PMID 29757368, 2018). "It was originally thought that inherited RUNX1 mutations cause leukemia predisposition because every HSC in an FPD/AML individual is already one mutation along the path to AML." (PMID 29326930, 2017). "The RUNX1 gene is required for definitive hematopoiesis, and is a frequent target of mutations and translocations in various leukemia types." (PMID 28611288, 2017). "While mutations directly affecting the RUNX1 protein are common in leukaemia, mutations in regulatory elements that affect RUNX1 expression remain enigmatic." (PMID 29042628, 2017).
leukemia (continued). "Runx1 is a well characterized transcription factor essential for hematopoietic differentiation and Runx1 mutations are the cause of leukemias." (PMID 28407681, 2017). "The three‐membered RUNX gene family includes RUNX1, a major mutational target in human leukemias, and displays hallmarks of both tumor suppressors and oncogenes." (PMID 27869314, 2017). "It will be of interest to examine CASC15 in other leukemia subtypes with RUNX1 loss-of-function, and these experiments are the focus of future studies." (PMID 28724437, 2017). "Does the presence of a DNMT3A mutation, which in a normal individual only modestly increases the risk of leukemia, confer a much greater risk in the context of an inherited RUNX1 mutation?" (PMID 29326930, 2017). "Here we will focus on RUNX1, a leukemia predisposition gene that is also frequently mutated in sporadic leukemia." (PMID 29326930, 2017). "The transcription factor Runx1 is essential for definitive haematopoiesis, and the RUNX1 gene is frequently translocated or mutated in leukaemia." (PMID 29042628, 2017). "In leukemia RUNX1 gene is one of the most frequent targets of mutations and chromosomal rearrangements." (PMID 26901859, 2016). "Traditionally, loss of RUNX1 leads to impaired differentiation and is followed by leukemia development." (PMID 26910834, 2016). "Despite the causative role of the RUNX1/RUNX1T1 fusion gene in leukaemia initiation, additional genetic lesions are required for disease development." (PMID 27252013, 2016). "Mutations in RUNX1 cause defects in different blood lineages in human patients and mouse models, including leukemia and blood clotting defects due to a shortage of platelet-producing megakaryocytes." (PMID 26808730, 2016). "In conclusion, our study enhances the understanding of the molecular mechanism underlying ETV6/RUNX1-mediated attenuation of B-cell differentiation and offers the opportunity to identify new targets for development of therapeutic approaches to leukemia." (PMID 26580398, 2015). "For example, a missense mutation in RUNX1, which encodes a transcription factor frequently mutated in leukaemia, was found only in M1." (PMID 24399611, 2014). "RUNX1 is the most frequently mutated gene in human leukaemia and many studies have focused on its tumour suppressive function in haematopoietic malignancies." (PMID 24967588, 2014). "Common to all RUNX1-ETO animal models developed so far is the inability of the fusion protein to induce overt leukemia, unless additional mutations are present." (PMID 23344057, 2013). "The importance of RUNX1 in hematopoiesis and its TSG function in leukemia are well established, although RUNX1 gene amplifications and gain-of-RUNX1 function mutations have been postulated to have leukemogenic effects." (PMID 24124450, 2013). "Although sufficient for in vitro immortalization, RUNX1-ETO requires additional cooperating mutations to induce leukemia in vivo." (PMID 24130502, 2013). "RUNX1 is known to play critical roles in hematopoiesis, and is commonly mutated in leukemia as a tumor suppressor, including in MLL-ENL driven leukemias." (PMID 23352661, 2013). "RUNX1 resides on human chromosome 21 and is often involved in leukemia associated chromosomal translocations including 8;21 acute myeloid leukemia (AML) and 12;21 acute lymphoblastic leukemia (ALL)." (PMID 23717578, 2013). "Searching for RUNX1 in published results across all studies revealed differential expression for groups of leukemias and that mutations in RUNX1 occur frequently." (PMID 22720055, 2012). "In t-AML a 40kb deleted MCR pointed to RUNX1 on 21q22, a gene coding for a transcription factor implicated in frequent rearrangements in leukemia and in familial thrombocytopenia." (PMID 21339820, 2011). "RUNX1 is a TF associated with several types of leukemia and is known to bind to T cell receptor enhancers." (PMID 21736739, 2011).
leukemia (continued). "One of the most commonly mutated genes in leukemia is RUNX1, which encodes a DNA-binding subunit of the heterodimeric core-binding factors." (PMID 22145044, 2011). "Chromosomal translocations and mutations in RUNX1 can be initiating events that occur in HSCs, after which leukemias clonally evolve through the acquisition of secondary mutations." (PMID 22145044, 2011). "We have used multiple microarray platforms and bioinformatic techniques to help identify these biological pathways to aid in the understanding of why RUNX1 mutations lead to leukemia." (PMID 18671852, 2008). "RUNX1 is one of the most frequent targets of somatic mutations in leukemia and is mutated in an autosomal dominant disorder affecting platelets and predisposing to leukemia development." (PMID 18671852, 2008). "Finally, RUNX1 plays a crucial role in haemotopoiesis and mutations at this gene have been connected to a variety of haematological malignancies, including leukemia; the variant rs71329093 has been found to associate with platelet count and crit." (PMID 41332835, 2025). "Prenatal exposure to corticosteroids within a critical time window may therefore increase the risk of developing ETV6::RUNX1+ preleukemic clones and potentially leukemia after birth." (PMID 40243620, 2025). "Next, we tested whether RUNX1 loss alters CHK1-inhibitor response in human SRSF2-mutant leukemia cells." (PMID 41279606, 2025). "Moreover, RUNX1::RUNX1T1 AML cells are addicted to ERG and RUNX1 with a disbalanced expression in favor of RUNX1::RUNX1T1 causing leukemia cell death." (PMID 39857993, 2025). "RUNX1 mutations are observed in various types of leukemia, as well as other hematological diseases." (PMID 39151099, 2025). "Still, overall, RUNX1 mutations are well-known in leukemias, suggesting that this hotspot may have functional effects that deserve further investigation." (PMID 38473427, 2024). "However, in leukemia, the majority of the characterized RUNX1 mutations, with the exception of AML-ETO fusion protein, diminish or abolish RUNX activity." (PMID 38630262, 2024). "The reported mutations of MGA in pediatric RUNX1::RUNX1T1 leukemias are heterozygous, somatic mutations at variable variant allele frequencies and result in the deletion of the MYC-like bHLH domain, potentially resulting in a protein with altered or abolished function." (PMID 38454121, 2024). "The exclusivity of NPM1 and RUNX1 mutation in AML might suggest that RUNX1 mutation shares a similar role with NPM1 mutations in leukaemia development." (PMID 37188777, 2023). "Consequently, the chromosomal rearrangements and gene mutations involving RUNX1 lead to various leukaemia types." (PMID 37759525, 2023). "In addition to translocations, sporadic somatic mutations in RUNX1, either monoallelic or biallelic, are found in multiple leukemias, including AML (6–33%)." (PMID 37190015, 2023). "In addition, the activity of FOXO1 has been reported to affect the antineoplastic drug sensitivity of AML cells, and has been proposed as a therapeutic for leukemia with RUNX1 mutations." (PMID 38007419, 2023). "Thus, it was proposed that the lower residual activity of the wild-type RUNX1 protein resulted in genomic instability and impacted the risk for leukemia development in FPD/AML patients." (PMID 37190015, 2023). "For instance, RUNX1 mutations seem to be observed with a relatively frequent occurrence in leukemias with MPAL immunophenotype leading to a discussion of whether a case should be classified as MPAL or AML with RUNX1 mutation (a provisional entity in WHO 2016)." (PMID 35380407, 2022).
leukemia (continued). "Furthermore, pharmacological inhibition of NF-κB signaling reduced tumorigenesis in vivo by suppressing NF-κB-mediated excessive proliferation of AML1/RUNX1 mutated leukemia cells." (PMID 35884618, 2022). "Regarding germline mutations, RUNX1 was first associated with leukemia predisposition in 1999." (PMID 35884491, 2022). "Since all these data suggest that RUNX family members are crucial for normal hematopoiesis and change in their structure or expression can cause leukemia development, the aim of this study was to evaluate RUNX1 and RUNX3 relative expression level in adult acute lymphoblastic leukemia cases." (PMID 36005134, 2022). "Furthermore, it is well known that mutation of the transcription factor (TF) RUNX1/AML1 is observed frequently in patients with myelodysplastic syndrome and leukemia, and the mutation is linked to the expression of rRNA and ribosomal proteins." (PMID 36033520, 2022). "RUNX1 mutations in leukemia are thought to play a role in differentiation dysregulation in this “2-hit” model, albeit removing dysregulated wild-type RUNX1 in leukemia cells also causes a drastic reduction in cell numbers." (PMID 34434964, 2021). "The outcome of these mutations indicates that the level of RUNX1 is critical for leukemia." (PMID 34359655, 2021). "By analysing deep sequencing of AML patient samples that have no identifiable mutations in the RUNX1 coding region or in other leukaemia genes, mutations in REs that lead to dysregulated RUNX1 expression may be discovered." (PMID 34440349, 2021). "Besides the causative RUNX1 mutation in leukemia diseases, dysregulated wild-type RUNX1 also contributes to leukemia development." (PMID 34434964, 2021). "Recurrent mutations in RUNX1 have been observed in estrogen receptor-positive luminal breast cancer, which, similarly to leukemia, may be considered as a stem-cell disorder." (PMID 34831147, 2021). "Besides cooperation with signal transduction mutations, RUNX1‐ETO was also found to cooperate with the WT1 transcription factor with the expression of both rapidly causing leukaemia." (PMID 34766123, 2020). "This might be the reason why we missed novel recurring but rare mutations in RUNX1/RUNX1T1-rearranged leukemia [CCND2 (6–12%), MGA (8%)]." (PMID 31896782, 2020). "The presence of these mutations may predispose to acquisition of secondary mutations in CSF3R and RUNX1 and the development of leukemia." (PMID 32821971, 2020). "RUNX1 mutations disappeared and leukemia cutis ensued after multiple chemotherapies." (PMID 33292606, 2020). "WT and 3 selected leukemia-causing mutant (i.e., K83E, S114L and R139Q) RUNX1 were included." (PMID 31048839, 2019). "Such a “good” mutant could provide an elevated RUNX1 activity and counteract a leukemia-causing RUNX1 mutation." (PMID 31048839, 2019). "Insufficient activity of RUNX1 causes hampered hemopoietic differentiation, accumulation of undifferentiated blood cells, and eventually, upon acquisition of other mutations, onset of the leukemia." (PMID 31048839, 2019). "Hence, while ETV6-RUNX1 expression in primary human leukemia cells associates with altered expression of a substantial fraction of the RUNX1 target genes, reduced function of IKZF1 or PAX5 had limited impact on the expression of their target genes." (PMID 31381561, 2019). "The ultimate goal is to develop a RUNX1 activation therapy for treatment of RUNX1 mutated leukemia." (PMID 31048839, 2019). "The overall levels of RUNX1 activity seem to correlate with the predisposition to leukemia." (PMID 31048839, 2019). "We hypothesize that a RUNX1 mutation that binds to DNA stronger could counteract those leukemia-causing RUNX1 mutations." (PMID 31048839, 2019). "The contribution of RUNX1 mutations in the pathogenesis of myeloid transformation in ASXL1-mutated leukemia, however, remains unclear." (PMID 31640815, 2019).